PAK3 (p21 (RAC1) activated kinase 3)
Description:
Serine/threonine protein kinase that plays a role in a variety of different signaling pathways including cytoskeleton regulation, cell migration, or cell cycle regulation. Plays a role in dendrite spine morphogenesis as well as synapse formation and plasticity. Acts as a downstream effector of the small GTPases CDC42 and RAC1. Activation by the binding of active CDC42 and RAC1 results in a conformational change and a subsequent autophosphorylation on several serine and/or threonine residues. Phosphorylates MAPK4 and MAPK6 and activates the downstream target MAPKAPK5, a regulator of F-actin polymerization and cell migration. Additionally, phosphorylates TNNI3/troponin I to modulate calcium sensitivity and relaxation kinetics of thin myofilaments. May also be involved in early neuronal development. In hippocampal neurons, necessary for the formation of dendritic spines and excitatory synapses; this function is dependent on kinase activity and may be exerted by the regulation of actomyosin contractility through the phosphorylation of myosin II regulatory light chain (MLC) (By similarity).
Synonyms: PAK-3; OPHN3; hPAK3; bPAK; ARA; MRX30; MRX47; PAK3beta; XLID30; beta-PAK
Tractability: Small molecule: a structure with a bound ligand is known; a high-quality ligand is known; it belongs to a druggable protein family. Antibody: its Gene Ontology location is reachable by antibodies, with high confidence. PROTAC: UniProt records ubiquitination sites on it; ubiquitination databases record sites on it; its protein half-life has been measured; a small molecule that binds it is known.
Target class: Protein Kinase; STE protein kinase PAKA subfamily; Enzyme; STE protein kinase group; Kinase; STE protein kinase STE20 family
Chemical probes: G-5555 (high quality)
Safety:
Unwanted effects reported when the protein is acted on. In parentheses: how it was acted on, where the effect was seen, and who reports it.
cardiac arrhythmia (cardiovascular system; source: Lamore et al. (2017))
Gene: Protein-coding gene on chromosome X (110,944,285 to 111,227,361, forward strand). Ensembl gene ENSG00000077264.
Subcellular location: Cytoplasm
Subcellular location (Human Protein Atlas): Vesicles
Pathways (Reactome):
Signal Transduction: CDC42 GTPase cycle; MAPK6/MAPK4 signaling; RAC1 GTPase cycle; RHO GTPases activate PAKs; RHOJ GTPase cycle; RHOU GTPase cycle; VEGFR2 mediated vascular permeability
Developmental Biology: Activation of RAC1; Ephrin signaling; Sema3A PAK dependent Axon repulsion
Immune System: CD209 (DC-SIGN) signaling; CD28 dependent Vav1 pathway; Generation of second messenger molecules
Gene Ontology:
Molecular function: MAP kinase kinase activity; protein binding; protein serine/threonine kinase activity; ATP binding; protein kinase activity; protein serine kinase activity
Biological process: regulation of actin filament polymerization; axonogenesis; cell migration; cellular response to starvation; dendrite development; dendritic spine morphogenesis; ephrin receptor signaling pathway; regulation of actin cytoskeleton organization; regulation of axonogenesis; regulation of MAPK cascade; stimulatory C-type lectin receptor signaling pathway; synapse organization; MAPK cascade; regulation of actin filament organization
Cellular component: cytoplasm; cytosol; plasma membrane
Gene-disease validity (ClinGen):
ClinGen rates the evidence that PAK3 causes each of these diseases.
X-linked syndromic intellectual disability (X-linked): Definitive. A syndromic intellectual disability with an X-linked mode of inheritance.
Homologues: Orthologues: chimpanzee PAK3 (100% identical), pig PAK3 (99% identical), macaque PAK3 (99% identical), guinea pig PAK3 (99% identical), rat Pak3 (99% identical), mouse Pak3 (99% identical), rabbit PAK3 (96% identical), tropical clawed frog pak3 (95% identical), Drosophila melanogaster Pak (65% identical). Paralogues in human: PAK1 (81% identical), PAK2 (74% identical), PAK5 (38% identical), PAK4 (37% identical), PAK6 (36% identical), MAP3K19 (26% identical), MAP3K1 (25% identical), SLK (24% identical), MAP4K3 (24% identical), MAP4K4 (24% identical), TAOK1 (24% identical), TNIK (24% identical), and 23 more.
Diseases named in the same sentence as PAK3 in open-access papers:
PAK3 is named in the same sentence as 63 diseases in open-access papers, as found by Europe PMC text mining. Sharing a sentence is not in itself a finding about the gene and the disease. The quoted sentences say what the papers report.
Intellectual disability (17 papers, 2010 to 2025). "PAK3 testing should be considered in families with suspected X‐linked sleep‐related hypermotor epilepsy and intellectual disability, including for mosaicism in mildly affected females." (PMID 39806575, 2025). "Almost all reported cases with PAK3 pathogenic variants have intellectual disability, consistent with the mild or moderate intellectual disability of the affected brothers reported here." (PMID 39806575, 2025). "Both of her hemizygous sons will transmit the PAK3 pathogenic variant to any daughters, and given they only have mild or moderate intellectual disability, counseling will be recommended." (PMID 39806575, 2025). "In humans, a recent study highlighted that the function of PAK3 in cell migration was associated with brain morphological changes in patients with intellectual disability and corpus callosum agenesis." (PMID 33306168, 2022). "PAK3 is a critical regulator of synapse formation and plasticity in the hippocampus, whereas a mental retardation-linked PAK3 mutant causes elongated dendritic spines and reduced mature synapses, spontaneous EPSCs, and reduced AMPAR levels." (PMID 32825197, 2020). "Further genes of the Rho GTPase family, like OPHN1, ARHGEF6 and PAK3, have been implicated in non-syndromic intellectual disability and play a role in spine morphology and synaptic plasticity." (PMID 29685133, 2018). "Based on interactions with α-PIX and PAK3, known human X-linked intellectual disability genes, GIT1 was suggested to regulate cognitive function through regulation of synaptic plasticity, and experiments in primary neurons have indicated synaptic roles." (PMID 29554125, 2018). "PAK3 mutations in humans leads to nonsyndromic mental retardation characterized by selective cognition deficits." (PMID 25379771, 2014). "For example, PAK3 has been implicated in neuronal development and plasticity, and its mutation has been identified in X-linked mental retardation patients." (PMID 22485184, 2012). "PAK3 mutations targeting the kinase domain of the protein, most frequently found in patients with intellectual disability and cortical malformations, should therefore severely impair the migration of cortical INs in infants and the formation of normal cortical circuits." (PMID 38454080, 2024). "PAK3-related mental retardation also represents a rare cause of X-linked MR." (PMID 33306168, 2022). "Because the GIT1 partner α-PIX and its partner PAK3 are known human X-linked intellectual disability genes, it was expected that GIT1 might be important for learning and memory." (PMID 29554125, 2018). "Of interest, this dimerization is inhibited by mutations in PAK3 that lead to mental retardation, suggesting that PAK1 levels may contribute to spine reductions through this mechanism." (PMID 23613712, 2013). "Furthermore, p21Cip1-activated kinase 3 (Pak3), which is associated with non-syndromic mental retardation in humans, and Musk, a receptor tyrosine kinase that plays a role in neuromuscular junction organization, were found to be covalently conjugated to NEDD8 in vivo." (PMID 20596523, 2010). "While intellectual disability, psychiatric and behavioral problems, and facial dysmorphism are common and well‐recognized in PAK3‐related disease, seizures are less commonly reported, in only 19% of cases." (PMID 39806575, 2025). "Importantly, defects in PAK3 as well as in Patched domain-containing protein 1 (PTCHD1), another validated miR150-5p target, are associated with intellectual disability in humans, and PTCHD1 deficiency causes synaptic and cognitive dysfunctions in mice." (PMID 35563859, 2022). "Protein kinases such as Pak3, Limk1, ERK, and RSK2 have been implicated in intellectual disability." (PMID 35011609, 2021).
cognitive deficits (8 papers, 2014 to 2024). "Mutations of PAK3, a p21-activated kinase, are associated in humans with cognitive deficits suggestive of defective cortical circuits and with frequent brain structural abnormalities." (PMID 38454080, 2024). "This suggests that EVs mediate the transfer of miR-150-5p to neurons, and consequent PAK3/PTCHD1 downregulation may be implicated in cognitive impairments of MS patients." (PMID 35563859, 2022). "Some migration-associated mutations were found in other brain activity genes involved in sleep and cognitive disorders in mice and humans (prominently XPNPEP1 and PAK3)." (PMID 35143486, 2022). "Considering that PAK3 regulates synapse formation and plasticity, this result suggests that disruption of synaptic NMII/actin could contribute to early synapse dysfunction and cognitive impairment in these diseases." (PMID 32825197, 2020).
lung carcinoma (8 papers, 2015 to 2025). "Previous research has shown that hsa-miR-543, in collaboration with hsa-miR-495, regulates lung cancer metastasis by targeting the 3′UTR of PAK3." (PMID 39941924, 2025). "Functional SMAD4 is a tumor suppressor and its inactivation promotes lung cancer metastasis through de‐repression of PAK3 by miRNA regulation." (PMID 36161776, 2023). "We conclude that downregulation of Smad4 derepresses the PAK3-JNK-Jun pathway via attenuated production of miR-495/miR-543 in lung cancers." (PMID 34381046, 2021). "Given the inverse correlation between SMAD4 and PAK3 in PK/SPK lung cancer cells, we wondered how PAK3 signaling affects cell migration and invasion." (PMID 34381046, 2021). "Taken together, we conclude that Smad4-mediated PAK3-JNK-Jun activation via regulation of miRNA in lung cancers appears to be a mechanism in the development of metastatic human lung cancers." (PMID 34381046, 2021). "In summary, this study identifies an effector of Smad4, PAK3, and a de novo miRNA-mediated mechanism in the regulation of lung cancer metastasis." (PMID 34381046, 2021). "The action of Smad4 in the regulation of PAK3 offers a tool for lung cancer prognosis." (PMID 34381046, 2021). "To determine whether PAK3 may regulate JNK-Jun activities in lung cancer cells, we checked the expression of p-JNK and p-Jun in PK and SPK cells." (PMID 34381046, 2021). "An inverse correlation between Smad4 and PAK3 pathway components is observed in human lung cancer." (PMID 34381046, 2021). "These microRNAs (miRNAs) directly bind to the PAK3 3′UTR for blockade of PAK3 production, ultimately regulating lung cancer metastasis." (PMID 34381046, 2021). "Our data suggest that the PAK3, a downstream effector of SMAD4, mediates lung cancer cell metastasis." (PMID 34381046, 2021). "Our results demonstrate that the upregulation of PAK3 by Smad4 LOF in SPK mice was achieved by attenuating SMAD4-dependent transcription of miRNAs that negatively regulate PAK3 expression, ultimately enhancing lung cancer metastasis." (PMID 34381046, 2021). "Therefore, our data suggest that PAK3 acts in signal transduction between Smad4 and the JNK-Jun signal pathway in lung cancer cells." (PMID 34381046, 2021).
pancreatic cancer (6 papers, 2019 to 2025). "PAK3 can also promote pancreatic cancer stem cell phenotypes by activating the Akt-GSK3β-β-catenin signaling pathway." (PMID 34976179, 2022). "PAK3 acts on Ser473-Akt kinase regulating the Akt-GSK3β-β-catenin signaling in several pancreatic cancer cell lines." (PMID 33521362, 2021). "p21-activated kinase 3 (PAK3) controls Akt-GSK3β (Glycogen Synthase Kinase 3 beta)-β-catenin signaling in pancreatic cancer cells." (PMID 31416295, 2019). "At present, it has been confirmed that PAK3 may be involved in the development of thymus carcinoid, gastric cancer and pancreatic cancer, and PAK3 is considered a tumor enhancer that can promote the occurrence and development of such cancers." (PMID 34976179, 2022). "Except for IL22RA1 and PAK3, most of them were up-regulated in pancreatic cancer." (PMID 33869254, 2021). "KIAA1324 and PAK3 are associated with kidney renal clear cell carcinoma, hepatocellular carcinoma, and other tumors, but their effect on pancreatic cancer has not been well researched." (PMID 37505298, 2024). "Interestingly, in pancreatic cancer, PAK4 exhibited the highest frequency of alterations (10%), a notable increase compared to PAK2 (4%) and PAK3 (1%), while PAK1, PAK5, and PAK6 were altered in fewer than 1% of cases." (PMID 39756822, 2025).
depression (4 papers, 2020 to 2023). "Patients bearing this PAK3 variant were diagnosed with mild non-syndromic X-linked ID with a few individuals also presenting neuropsychiatric problems such as aggressiveness, antisocial behavior, psychosis, depression or epilepsy." (PMID 36937657, 2023). "PAK1 and PAK3 mRNA levels are significantly reduced in the post-mortem brain of subjects affected with depression." (PMID 36937657, 2023). "Interestingly, two independent studies showed that Pak3 expression is significantly reduced in the hippocampus and frontal cortex of postmortem brains from patients with depression and AD." (PMID 31947657, 2020).
epilepsy (4 papers, 2022 to 2025). A brain disorder characterized by episodes of abnormally increased neuronal discharge resulting in transient episodes of sensory or motor neurological dysfunction, or psychic dysfunction. "This is the first reported association of a PAK3 pathogenic variant with sleep‐related hypermotor epilepsy." (PMID 39806575, 2025). "Variations in the GluA1 subunit of AMPA receptors, one of PAK3-specific targets, are associated with moderate to severe ID and sometimes epilepsy, ASD, ADHD and movement disorders." (PMID 36937657, 2023). "This study is the first to describe sleep‐related hypermotor epilepsy in PAK3‐related disease." (PMID 39806575, 2025). "Thirty-five patients manifested epilepsy without any other comorbidity and seven of them (20.0%) carried variants in six genes, namely KCNQ2, NALCN, PAK3, PRRT2, SCN1A, and SLC2A1 that are among the well-known genes causing epilepsies or syndromes including epilepsy." (PMID 36035117, 2022). "PAK3 mutations can lead to ID of varying severity and may be associated with autistic traits, ADHD, paranoid psychosis, aggressiveness, self-harm, and other neurological signs such as epilepsy and motor disorders." (PMID 36937657, 2023). "Notably, clinical features usually observed in MR, such as autistic features, epilepsy or sleep disorder, have not been frequently observed in PAK3-related disorders, suggesting the distinguishable phenotypes of PAK3-related MR from other X-linked MR syndromes." (PMID 33306168, 2022).
glioblastoma (3 papers, 2024 to 2025). The most malignant astrocytic tumor (WHO grade IV). "Since TIMAP is also predominantly expressed in the nervous system and is a prognostic marker in glioblastoma multiform and head and neck cancer, it is plausible that it might be associated with PAK3 regulation." (PMID 41170526, 2025). "Furthermore, PAK3 represents a critical signature gene in the original neural subtype of glioblastoma (GBM), impacting its proliferation, differentiation, and growth." (PMID 40332759, 2025).
glioma (3 papers, 2023 to 2024). A benign or malignant brain and spinal cord tumor that arises from glial cells (astrocytes, oligodendrocytes, ependymal cells). "PAK3 is a vital marker gene for the proneural subtype of glioma, affecting proliferation, differentiation, and growth." (PMID 37963970, 2023). "Induced cytoskeletal changes in cells, PAK3 has been reported as a signature gene of the glioma cells in promoting proliferation, growth, and differentiation." (PMID 37190165, 2023). "Importantly, PAK3 has been reported as a signature gene of the glioma pro-neural subtype affecting proliferation, growth, and differentiation." (PMID 37190165, 2023).
liver cancer (3 papers, 2015 to 2025). An epithelial or non-epithelial malignant neoplasm that arises from the liver. "First, we detected the expression of EMT-related transcription factors in transfected liver cancer cells by qRT-PCR assay, and the results showed that the expression of EMT-related transcription factors increased with the increased expression of PAK3." (PMID 34976179, 2022). "The malignant biological behavior of liver cancer is closely related to the occurrence of EMT, while the mechanism underlying the relationship between PAK3 and EMT has not yet been reported." (PMID 34976179, 2022).
microcephaly (3 papers, 2022 to 2023). A congenital or acquired developmental disorder in which the circumference of the head is smaller than normal for the person's age and sex. "Several loss of function and splice mutations in the PAK3 gene have been identified in different families of X-linked mental retardation with certain specific clinical features, such as microcephaly, mild to moderate mental retardation, oral motor dysfunction and aggressive behavior." (PMID 33306168, 2022). "Indeed, microcephaly is now often associated with PAK3 variations." (PMID 36937657, 2023). "The mutation located near the PIX-binding sequence in PAK3 was recently described in a girl with ID, microcephaly and immunological disease but without the biochemical analysis of the variant." (PMID 36937657, 2023). "Notably, Pak1/Pak3 double-knockout mice showed a robust microcephaly phenotype in postnatal brain growth." (PMID 33306168, 2022).
Alzheimer disease (2 papers, 2021 to 2024). A progressive, neurodegenerative disease characterized by loss of function and death of nerve cells in several areas of the brain leading to loss of cognitive function such as memory and language. "All of these genes are known to be involved in neurological diseases; AMOT is implicated in Alzheimer’s disease and PAK3 is associated with inherited X-linked intellectual disability." (PMID 38764741, 2024). "PAK3 mutations and PAK1 hyper-activation can cause MR such as X-linked MR (XLMR), Alzheimer disease (AD), and Huntington disease (HD)." (PMID 33796531, 2021).